PCK1 (phosphoenolpyruvate carboxykinase 1)
Diseases named in the same sentence as PCK1 in open-access papers (continued):
Sharing a sentence is not in itself a finding about the gene and the disease.
heart failure (1 paper, 2017). Inability of the heart to pump blood at an adequate rate to meet tissue metabolic requirements. "The modules related to the metabolic process of glucose and triglycerides were detected only in heart failure arising from PPCM, with upregulated G6PC, GPAM, and PCK1." (PMID 29160422, 2017).
Hypertension (1 paper, 2023). The presence of chronic increased pressure in the systemic arterial system. "The comparison of patients' data with the Mann–Whitney U test and Spearman's correlation analysis showed a close correlation between s-PCK1-Ab levels and hypertension." (PMID 37904164, 2023). "Second, we do not know the mechanism by which s-PCK1-Abs were increased in patients with DM and hypertension and were related to poor prognosis." (PMID 37904164, 2023). "We observed that s-PCK1-Ab levels were significantly higher in patients with hypertension than in those without." (PMID 37904164, 2023).
intrauterine growth retardation (1 paper, 2024). "Pigs with intrauterine growth retardation (IUGR) had significantly lower PCK1 mRNA levels in the jejunum and decreased CLDN expression compared to healthy pigs." (PMID 39272260, 2024).
invasive breast carcinoma (1 paper, 2024). A carcinoma that infiltrates the breast parenchyma. "For the five genes (LPL, PCK1, KRT6B, SFRP2, SHC2) that were differentially expressed between the datasets, we analyzed the alterations in metastatic breast cancer and invasive breast cancer genetic profiles." (PMID 38791477, 2024).
iron deficiency (1 paper, 2023). "However, emerging evidence suggests that iron deficiency also exerts inhibitory effects on the activity of alpha-glycerophosphate cytochrome c reductase and PCK1 in isolated rat hepatocytes, thereby implying a multifaceted impact of iron." (PMID 37887373, 2023). "In contrast, iron deficiency up-regulates the expression of G6Pase and PCK1 in rats, indicating a negative association between iron status and gluconeogenesis and glucose turnover." (PMID 37887373, 2023).
kidney tumor (1 paper, 2023). "Overexpression of PCK1 significantly inhibited the proliferation and survival in kidney tumor cell lines." (PMID 37553601, 2023). "In cancer cells, restoring gluconeogenesis by overexpression of PCK1 strongly blocked the proliferation and survival of kidney tumor cells." (PMID 37553601, 2023).
Lewis lung carcinoma (1 paper, 2025). "To investigate the regulation of Pck1 and Pdk3 by IL-6 in vivo, we compared B6 mice injected with Lewis lung carcinoma (LLC) cells that were either engineered to express IL-6 or to lack IL-6 expression." (PMID 40275022, 2025).
lipodystrophy (1 paper, 2020). A congenital or acquired disorder characterized by abnormal loss or redistribution of the adipose tissue in the body. "In contrast, knockdown of PCK1 expression in adipose tissue results in lipodystrophy in mice." (PMID 33045988, 2020).
obstructive sleep apnea syndrome (1 paper, 2023). Cessation of air flow during sleep due to upper airway obstruction. "AlphaLISA showed significantly higher serum antibody levels against recombinant PCK1 protein in patients with DM and cardiovascular disease than in healthy donors, but not in those with acute ischemic stroke, transient ischemic attack, or obstructive sleep apnea syndrome." (PMID 37904164, 2023).
primary aldosteronism (1 paper, 2025). An endocrine disorder characterized by excessive production of aldosterone by the adrenal glands. "Aldosterone also mediates the downregulation of phosphoenolpyruvate carboxykinase 1, perilipin, adiponectin, C1Q and the collagen domain in visceral adipose tissue, resulting in lower adiponectin levels and reduced insulin sensitivity in patients with primary aldosteronism." (PMID 40296149, 2025).
schizophrenia (1 paper, 2008). A major psychotic disorder characterized by abnormalities in the perception or expression of reality. "The C alleles of both rs4129219 and rs1040566 in each of the FBP1 and the PCK1 gene showed nominal association with elevated risk for schizophrenia." (PMID 18460190, 2008). "As we cannot draw firm conclusions with the current data further investigations with testing of more loci are required to clarify whether ENO2, FBP1, MAPK14 and PCK1 variants provide genetic support for the view that alterations in glucose metabolism are intrinsic to schizophrenia etiology." (PMID 18460190, 2008).
skin changes (1 paper, 2025). "Overall, PN modulates macrophage-fibroblast interactions via the CREB/PCK1 axis, enhancing collagen synthesis and counteracting age-related skin changes." (PMID 40943641, 2025).
squamous cell carcinoma (1 paper, 2021). A carcinoma arising from squamous epithelial cells. "The specific PCK1 p.P605H (c.1814C > A) mutation has only been reported in squamous cell carcinoma in the lung (sample name: TCGA-70-6722-01)." (PMID 34801052, 2021).
Stroke (1 paper, 2023). Sudden impairment of blood flow to a part of the brain due to occlusion or rupture of an artery to the brain. "PostE largely reduced the high expressions of PCK‐1 (***p < .001 at 1 day, *p < .05 at 3 days) as well as PCK‐2 (***p < .001 at 1 and 3 days) after stroke." (PMID 36448290, 2023).
thyroid (1 paper, 2022). "Researchers found that thyroid hormones can directly elevate the expression of gluconeogenesis rate-limiting enzymes PCK1 and G6PC." (PMID 34991199, 2022).
Wilms tumor (1 paper, 2021). An embryonal neoplasm characterized by the presence of epithelial, mesenchymal, and blastema components. "For Family 2 (Wilms tumor), the top-five ranked genes were FAM8A1, TRPM3, PAH, PCK1, and PCK2." (PMID 34624066, 2021).
tumor (115 papers, 2012 to 2026). "PCK1 expression was significantly associated with smaller tumor diameter, less bowel wall invasion, and history of alcohol intake." (PMID 37062825, 2023). "According to Kaplan-Meier and log-rank test survival analysis, we found that factors significantly associated with DFS were tumor diameter (P = 0.011), tumor stage (P = 0.001), lymph node metastasis (P = 0.001), and PCK1 expression (P = 0.03)." (PMID 37062825, 2023). "For example, tumor cells with RAS mutations can enhance lipid synthesis by upregulating the activity of phosphoenolpyruvate carboxykinase 1 (PCK1)." (PMID 35392570, 2022). "Considering that the murine subcutaneous xenograft model using PLC/PRF/5 cell is difficult to achieve, we examined the effects of PCK1 deficiency on tumor growth in an orthotopic transplantation HCC mouse model." (PMID 30717766, 2019). "Network topology and machine learning approaches consistently highlighted ACACB, ADH4, and PCK1 as core hub genes, all of which showed significant differential expression between tumor and normal tissues and demonstrated strong diagnostic performance (AUC > 0.87)." (PMID 42032347, 2026). "Therefore, the underlying molecular mechanisms of PCK1 development in different tumor tissues and disease stages should be fully investigated." (PMID 39578429, 2024). "PCK1 was highly expressed in the low-risk group, suggesting that it may play an essential role in the tumor microenvironment." (PMID 37298343, 2023). "Moreover, tumor cells with RAS mutation enhance cholesterol synthesis by increasing phosphoenolpyruvate carboxykinase 1 (PCK1)." (PMID 36721212, 2023). "PCK1 expression was significantly associated with smaller tumor diameter (tumor diameter ≤ vs. > 5 cm; 14.13% vs. 6.76%, P = 0.009), less bowel wall invasion (T stage) (T1 + T2 vs. T3 + T4; 23.07% vs. 8.00%, P = 0.002), and history of alcohol intake (never vs. ever; 12.40% vs. 4.81%, P = 0.031)." (PMID 37062825, 2023). "In the mammalian liver, PCK1 accounts for over 95% of gluconeogenesis activity, is upregulated in colon and melanoma cancers, and is associated with increased glucose consumption to support anabolic metabolism and tumor growth." (PMID 30717766, 2019). "Among several important key metabolic regulators, phosphoenolpyruvate carboxykinase 1 (PCK1) plays a central role in reprogramming glucose metabolism in tumor-repopulating cells (TRCs)." (PMID 40565936, 2025). "Immunohistochemical database analysis reveals that EIF4EBP1, RIMKLA, and BIRC5 are highly expressed in tumour tissues, while the PCK1, PLG, PEBP1, and CAT show a lower expression in tumour samples." (PMID 40591061, 2025). "Recent research has yielded numerous findings on PCK1 in tumor studies, yet its role remains controversial, exhibiting both tumor-suppressive and oncogenic properties across various malignancies." (PMID 40755786, 2025). "By contralling the glycolytic activity of T cells via PCK1, circRNA can alter the metabolic competition that occurs between tumor cells and T cells within the tumor microenvironment." (PMID 40296917, 2025). "Intravenous delivery of the Insig1/2 loop 1 peptide effectively attenuated tumor growth, prolonged mouse survival, inhibited the PCK1‐Insig‐SREBP‐lipid production axis, and increased cell apoptosis in tumor tissues." (PMID 40959854, 2025). "It has been found that overexpression of PCK-1 in T cells can promote glycolysis and restore the anti-tumor effect of T cells." (PMID 40296917, 2025). "Blocking PCK1 function in combination with anti-PD-1 antibody therapy exhibits an additive therapeutic effect on tumor growth." (PMID 40567603, 2025). "In murine tumor models, blocking Pck1-mediated glycogen synthesis through intraperitoneal GPI injection or oral 3-MPA administration accelerates tumor growth." (PMID 40155378, 2025).
tumor (continued). "Concurrently, the SIRT2-mediated activation of phosphoenolpyruvate carboxykinase 1 (PEPCK1) promotes glycolysis and reduces E-cadherin expression, facilitating tumor cell invasion." (PMID 41428704, 2025). "At this time, tumor cells maintain their energy requirements through PCK1-mediated metabolic reprogramming in response to changes in the microenvironment and bioenergy fluctuations." (PMID 39578429, 2024). "Considering the expression, activity, and functional differences of PCK1 in various tumor types, precision, and personalization are important development directions for metabolic therapy." (PMID 39578429, 2024). "PCK1 overexpression not only enhances its anti-tumor function but also prolongs the lifespan of memory CD8 + T cells through metabolic reprogramming of T cells." (PMID 39578429, 2024). "In addition, PCK1 is involved in the biosynthesis of serine, an amino acid that is the major substrate for one-carbon metabolism; is vital for nucleotide synthesis, methylation, and antioxidation; and is associated with the migration and proliferation of tumor cells." (PMID 39262325, 2024). "The inhibition of YAP1 induces the restriction of PCK1 on gluconeogenesis and restores the anti-tumor effect on HCC." (PMID 38550587, 2024). "For example, PCK1 is involved in the proliferation and migration of various tumor cells and vascular endothelial cells through metabolic and nonmetabolic effects." (PMID 39262325, 2024). "Recently, in the context of the Warburg effect, PCK1 has shown its critical role in meeting the rapid growth, proliferation, and metabolic demands of tumor cells." (PMID 39578429, 2024). "The study of PCK1 not only contributes to the understanding of the metabolic reprogramming mechanism of tumor cells, but also provides new potential targets for tumor diagnosis and treatment." (PMID 39578429, 2024). "When PCK1 is stimulated by the complex and heterogeneous tumor microenvironment (TME), its expression is often dysregulated." (PMID 39578429, 2024). "As a key metabolic enzyme in gluconeogenesis and regulator of epigenetic modifications, PCK1 is known as a tumor suppressor gene." (PMID 39578429, 2024). "Metformin, an AMPK activator, compensates for AMPK inactivation caused by PCK1 loss by activating AMPK to induce cell cycle arrest and inhibit tumor growth." (PMID 39578429, 2024). "Research indicates that CD8+ T cells in the tumor microenvironment can increase PPP metabolism by overexpressing PCK1, inhibiting tumor growth." (PMID 39769177, 2024). "Cluster 2 expressed zone 1 and 2 metabolic genes, including Cyp2f2, Pck1, Cps1, and Hamp analogous to the reprogrammed tumor cell population observed in the early-stage LNP-CTNNB1 treatment setting." (PMID 39711542, 2024). "Our findings revealed that in drug-resistant tumor stem cells, the enzyme PCK1 enhances the phosphorylation of PYGL, leading to increased glycogen breakdown." (PMID 38871968, 2024). "By increasing the production of PEP through PCK1 overexpression, T cells are metabolically reprogrammed, T-cell function is restored, anti-tumor immune function is strengthened, and tumor growth is limited." (PMID 39578429, 2024). "Metabolic reprogramming of T cells by PCK1 can repair and increase the anti-tumor immune function of T cells and limit tumor growth." (PMID 39578429, 2024). "Collectively, these results support the finding that PCK1 deficiency alleviates SAM biosynthesis and H3K9me3 modification in S100A11, thereby promoting aberrant PI3K/AKT activation and tumor progression in human primary HCC." (PMID 37166978, 2023). "Our data provide evidence that PCK1 overexpression can inhibit tumor cell growth via down-regulation of UBAP2L Ser 454 phosphorylation and increasing autophagy, and that low PCK1 expression is an independent predictive factor for CRC recurrence and metastasis." (PMID 37062825, 2023). "Of note, endogenous knockout of PCK1 can partially antagonize the tumor inhibitory effects of A2B1 sgRNA in a HCC mouse model." (PMID 38017546, 2023).
tumor (continued). "High PCK1 expression was correlated with smaller tumor diameter and less bowel wall invasion (T stage)." (PMID 37062825, 2023). "The loss of PCK1 results in the enhancement of S100A11, which recruits AKT1 to facilitate the activation of the PI3K/AKT signaling pathway, thereby promoting tumor progression." (PMID 37166978, 2023). "PCK1 deficiency promotes hexosamine biosynthetic pathway (HBP)-induced protein O-GlcNAcylation in HCC cells, which enhances tumor proliferation." (PMID 37250903, 2023). "After the knockdown of PCK1 using siRNA, cell invasion and colony formation, as well as cell growth abilities of the tumour cells, were all decreased." (PMID 37407566, 2023). "As a downstream target of the PI3K-AKT signaling pathway, PCK1 can influence the SCAP/SREBP complex to regulate tumor lipid metabolism." (PMID 37062825, 2023). "In ccRCC, overexpression of PCK1 can suppress tumor progression via inhibition of lactate dehydrogenase A (LDHA), and patients with high PCK1 expression had better prognosis." (PMID 37062825, 2023). "This study shows that NFYAv2 exerts its anti-tumor effect only under glucose deprivation conditions by regulating PCK1 transcription." (PMID 36092708, 2022). "PCK1 encodes an imperative enzyme involved in the glycolysis/gluconeogenesis pathway and tumor immunity, and PCK1 catalyzes the first rate-limiting reaction of gluconeogenesis in the cytoplasm." (PMID 36325324, 2022). "Since tumor tissues have extremely low glucose concentrations compared to normal tissues, likely, the transcriptional regulation of PCK1 by NFYAv2 occurs predominantly in tumor tissues." (PMID 36092708, 2022). "A new study has revealed the specific lipid anabolic mechanism of tumor cells, suggesting that phosphoenolpyruvate carboxylated kinase 1 (PCK1) can be phosphorylated to achieve protein kinase activity." (PMID 36387147, 2022). "GPI1, TPI1, GAPDH, PGK1, and PKM2 were consistently upregulated in almost all tumor types, while PCK1, PCK2, and FBP1 were downregulated in tumors." (PMID 35246510, 2022). "Our study revealed that overexpression of PCK1 promoted cell proliferation, invasion and tumor stemness, and reduced the oxidative damage induced by vemurafenib." (PMID 36700470, 2022). "Under glucose deprivation conditions, as expected, the anti-tumor effects of gluconeogenesis were confirmed by induction of the expression of PCK1 and cleaved caspase-3 (CC3) in SK-Hep1 cells." (PMID 36092708, 2022). "The overexpression of many other amplified genes (e.g., AURKA, HRH3, MIR646, MRGBP, PCK1, PMEPA1, SLCO4A1-AS1, SOX18, TNFRSF6B) is associated with PDAC cell proliferation and tumour growth." (PMID 36289850, 2022). "The immunohistochemistry results showed that in the subcutaneous tumor tissues of nude mice inoculated with primary A2058 cells, the expression of PCK1 in the vemurafenib group was up-regulated compared with the DMSO group, while KEAP1 was inhibited." (PMID 36700470, 2022). "This study reveals a mechanism by which NFYAv2 promotes anti-tumor effects through the transcriptional regulation of PCK1 and induction of gluconeogenesis, indicating its importance as a therapeutic target for HCC." (PMID 36092708, 2022). "Pck1-LKO mice exhibited increased tumor sizes and number of tumor nodules, and DON treatment decelerated liver tumorigenesis without changing body weight." (PMID 34650217, 2021). "Our previous study demonstrated that PCK1 plays a tumor suppressor role in HCC via decreasing UDP-GlcNAc biosynthesis and global O-GlcNAcylation." (PMID 34650217, 2021). "The result was consistent with several studies suggesting that metformin remarkably suppressed the growth of PCK1-knockout tumor cells and inhibited tumor growth in an orthotropic HCC mouse model." (PMID 33865459, 2021). "Enhancing PEP production by overexpressing PEP carboxykinase 1 (PCK1) potentiated T cell anti-tumor activity, restricting tumor growth and prolonging survival of melanoma-bearing mice." (PMID 32642279, 2020).